NBN (nibrin)
Diseases named in the same sentence as NBN in open-access papers (continued):
Sharing a sentence is not in itself a finding about the gene and the disease.
Nijmegen breakage syndrome (continued). "Nijmegen Breakage Syndrome (NBS), an autosomal recessive genetic instability syndrome, is caused by hypomorphic mutation of the NBN gene, which codes for the protein nibrin." (PMID 22396666, 2012). "Women who have changes in the NBN gene, which codes for Nijmegen Breakage Syndrome (NBS), may be more likely to get BC." (PMID 39390525, 2024). "The variant c.657_661del in the NBN gene was found by chance in three of the subjects who were not related to the patients with Nijmegen breakage syndrome included in the registry." (PMID 36211402, 2022). "Nijmegen breakage syndrome (NBS, OMIM #251260) is an autosomal recessive disorder caused by hypomorphic mutations of the NBN gene, leading to microcephaly, growth retardation, immunodeficiency, a predisposition to cancer, premature aging, and neurodegeneration." (PMID 32630049, 2020). "Because of microcephalia, cytopenia and Slavic origin of the patient, Sanger sequencing on the NBN gene (Nijmegen breakage syndrome) was performed, no mutations were found." (PMID 31053147, 2019). "Fibroblasts from the progeroid Nijmegen breakage syndrome that express a truncated version of the nibrin protein (NBNp70) undergo premature senescence and have an enlarged morphology with high levels of senescence-associated β-galactosidase, although they do not have F-actin stress fibres." (PMID 25214013, 2015). "Lymphoid neoplasms associated with clinical syndromes are identified separately, including ataxia telangiectasia (AT) and Nijmegen breakage syndrome (NBS) with specific germline mutations in ATM and NBN, respectively." (PMID 38835969, 2024). "Hypomorphic mutations within Nibrin (NBN), which encodes a DDR protein, leads to Nijmegen Breakage Syndrome (NBS)—a rare autosomal recessive genetic disorder belonging to the chromosomal instability syndromes." (PMID 35269426, 2022). "Mutations in NBS1/NBN and RAD50, respectively, cause Nijmegen breakage syndrome (NBS) and an NBS-like disorder, with consequent microcephaly, but only the former suffers from immunodeficiency." (PMID 34502215, 2021). "The Nijmegen breakage syndrome (NBS; also known as Seemanova syndrome, OMIM: #251260) caused by biallelic germline inactivation of the NBN gene is the most common syndrome associated with the biallelic inactivation of proteins involved in the assembly of the MRN complex." (PMID 36982687, 2023). "In humans, homozygous hypomorphic mutations in MRE11, NBN (coding for the NBS1 protein) and RAD50 genes cause ataxia telangiectasia‐like disorder (ATLD‐OMIM:604391), Nijmegen breakage syndrome (NBS‐OMIM:251260) and NBS‐like disorder (NBSLD‐OMIM:613078), respectively." (PMID 35839783, 2022). "One of these is NBN, the gene for Nijmegen Breakage Syndrome (NBS)." (PMID 24928521, 2014). "Indeed, mutation of the genes encoding DNA ligase IV (LIG4), Nibrin (NBS1) or Aprataxin (APTX) results in DDR disorders, specifically LIG4 syndrome, Nijmegen breakage syndrome (NBS) and Ataxia oculomotor apraxia-1, in association with increased radiosensitivity." (PMID 26208712, 2015). "Since some of the newly identified interactors of the p26 and p70 fragments have not been found to interact with the full-length NBN, this suggests that these interactions may somehow contribute to the key biological phenomena underpinning the Nijmegen breakage syndrome." (PMID 25485873, 2014).
ovarian carcinoma (36 papers, 2016 to 2025). A malignant neoplasm originating from the surface ovarian epithelium. "Of the other genes associated with a FDR of less than 0.2, NBN is perhaps the best candidate ovarian cancer susceptibility gene." (PMID 39939714, 2025). "We furthermore identified a novel truncating variant in NBN, another candidate gene for ovarian cancer." (PMID 37013556, 2023). "The studies of MRN complex (RAD50, MRE11, NBN) mutations and ovarian cancer summarized above are contradictory and are insufficient to determine ovarian cancer risk." (PMID 35159349, 2022). "Two of them also developed ovarian cancer, which was associated with NBN germline mutations in our population." (PMID 33050356, 2020). "One biallelic NBN germline mutation was identified from 354 Russian women with ovarian carcinoma." (PMID 35159349, 2022). "The BARD1 and NBN genes were included in breast/ovarian cancer genetic panel tests, due to their breast cancer risk, despite the ovarian cancer risk for deleterious variants in these genes being unknown." (PMID 33086730, 2020). "NBN overexpression in breast and ovarian cancer cells leads to BRCA1-dependent olaparib resistance by promoting the phosphorylation of ATM-S1981 and homology-dependent recombination efficiency." (PMID 32226530, 2020). "The most frequent Nibrin (NBN) gene amplification in ovarian cancer tumors was observed in 15 out of 31 independent ovarian cancer patients." (PMID 32226530, 2020). "Two out of the four variants (NBN p.Asp95Asn and POLE p.Lys425Arg) were also detected in her sister, who developed ovarian cancer." (PMID 32522261, 2020). "NBN gene amplification in ovarian cancer tumors was observed in ovarian cancer patients." (PMID 35739271, 2022). "NBN overexpression in breast and ovarian cancer cells leads to BRCA1-dependent olaparib resistance." (PMID 35739271, 2022). "The MRN complex (MRE11, RAD50, and NBN) is implicated in nonhomologous end joining DNA repair and has rarely been reported in association with ovarian cancer." (PMID 35159349, 2022). "In the scope of the German Consortium for Hereditary Breast and Ovarian Cancer, other candidate genes (e.g., NBN, FANCM, XRCC2, and RECQL) are currently co-analyzed for research purposes and their significance in contributing to breast and ovarian cancer is under investigation." (PMID 34680878, 2021). "To corroborate NBN's CNAmp and overexpression in ovarian cancer, we further experimentally quantified NBN gene copy number and protein expression in an independent cohort of 31 serous ovarian cancer samples using droplet digital PCR and immunohistochemistry respectively." (PMID 32226530, 2020). "It is unclear whether NBN represents an ovarian cancer susceptibility gene, though a lack of the MRE11-RAD50-NBN complex has been reported in almost half of epithelial ovarian cancers." (PMID 37013556, 2023). "We also found that the copy number of OSGIN2, and NBN differed in RIPK2-altered and RIPK2-unaltered patients, and these genes were coexpressed with RIPK2 in ovarian cancer." (PMID 35477477, 2022). "For example, the BARD1 and NBN (miR-548ai targets), BRIP1 (miR-567 target), and CHEK2 (miR-943 target) genes, which are known to be involved in breast and ovarian cancers." (PMID 34768979, 2021). "We have further experimentally validated that overexpression of NBN, the most frequently amplified DDR gene in the pan-cancer cohort; can directly induce the olaparib resistance in both breast and ovarian cancer cell lines through activating the HDR pathway." (PMID 32226530, 2020). "For example, NBN and RAD50 were once considered to be associated with increased breast/ovarian cancer risk, but are no longer thought to be associated with cancer risk." (PMID 35626031, 2022).
ovarian carcinoma (continued). "Similarly, in relapsed platinum-sensitive high-grade ovarian cancer patients, therapeutic responses to Rucaparib were not restricted to BRCA-mutated tumors, and were observed in several patients with mutations to other HR genes including ATM, NBN, RAD51C, and RAD51D." (PMID 35205643, 2022).
prostate carcinoma (15 papers, 2014 to 2025). A carcinoma that arises from epithelial cells of the prostate gland. "A recent meta-analysis of studies in prostate cancer patients confirmed an association between the NBN germline alterations and increased prostate cancer risk (with OR = 6.4 and OR = 7.5 for the total and Caucasian populations, respectively)." (PMID 36982687, 2023). "In the current study, the set of genes (ATM, BRCA2, PALB2, and NBN) were those previously shown to be strongly associated with prostate cancer risk in this African ancestry sample." (PMID 38014910, 2023). "For example, recently it has been reported that the increased risk of breast and prostate cancer associated with the NBN (657del5) founder mutation is modified by the presence of a common missense variant in the NBN gene (E185Q)." (PMID 35101071, 2022). "ATM and NBN mutations have also been suggested to confer increased risk of prostate cancer and disease aggression." (PMID 25415046, 2014). "We examined the aggregate association of rare germline pathogenic/likely pathogenic/deleterious (P/LP/D) variants in ATM, BRCA2, PALB2, and NBN with a polygenic risk score (PRS) on prostate cancer risk among 1,796 prostate cancer cases (222 metastatic) and 1,424 controls of African ancestry." (PMID 38014910, 2023). "P/LP/D status aggregated across BRCA2, ATM, NBN, and PALB2 was strongly associated with risk of overall prostate cancer (OR = 4.51; 95% CI = 2.18–9.33; P = 4.75 × 10−05) and metastatic disease (OR = 6.92; 95% CI = 2.34–20.49; P = 4.76 × 10−04)." (PMID 38014910, 2023). "Genetics of prostate cancer have shown population specific features, particularly related mutations in HOXB13, NBN, and CHEK2; however mutations in BRCA2, mismatch repair genes, BRCA1, and ATM appear to contribute to risk in many populations." (PMID 34503195, 2021). "Taken together, we have shown that Andrographolide is an effective anti-cancer compound for prostate cancer by regulating genes associated to double-strand breaks such as ATM, NBN, BRCA2 BLM, PALB2 and BLM." (PMID 30800220, 2019). "Although there are currently no specific preventive recommendations for carriers of germline pathogenic variants in the MRN complex genes, this may change when meta-analyses or analyses in unselected cancer populations (e.g., carriers of NBN germline alterations with prostate cancer) are performed." (PMID 36982687, 2023). "In TALAPRO-1 phase 2 trial of talazoparib, a stable disease was achieved in patients with metastatic castration-resistant prostate cancers carrying the alterations in rarer HR repair genes including MRE11 and NBN." (PMID 36982687, 2023). "A combined therapy with olaparib and double immunotherapy (durvalumab and tremelimumab) showed its efficacy in patients with alterations in HR repair genes (including NBN, RAD50 and MRE11) in breast, ovarian, pancreatic, endometrial, or prostate cancers." (PMID 36982687, 2023). "Neither NBN gain nor NBN mRNA expression (or expression of its partner, KPNA2) was prognostic in the surgery cohort; consistent with previous publications on Nibrin expression in surgically treated prostate cancer patients." (PMID 25415046, 2014).
Fanconi anemia (12 papers, 2011 to 2022). Fanconi anemia (FA) is a hereditary DNA repair disorder characterized by progressive pancytopenia with bone marrow failure, variable congenital malformations and predisposition to develop hematological or solid tumors. "Appropriate prenatal counseling and partner testing is advised in situations involving mutations in genes that carry a recessive disease risk (those in the Fanconi anemia pathway, NBN, ATM, etc.)." (PMID 26484312, 2015). "HRD is an emerging biomarker defined by the mutations of BRCA1/2 genes, along with other Fanconi anemia pathway genes (RAD51D, NBN, and ATM)." (PMID 35983074, 2022). "Considerable evidence is now available suggesting that loss of one or several key genes involved in HR, among these ATM, CHEK1/2, NBN, RAD51 and genes of the Fanconi Anemia complementation group, is associated with sensitivity of cancers to platinum drugs and PARP inhibitors." (PMID 27756336, 2016). "These genes include the Fanconi anemia pathway genes: FANCA, PALB2, BRIP1, RAD51C and XRCC2 and non-Fanconi anemia genes: ATM, CHEK2, NBN, RAD50, RAD51B, and RAD51D." (PMID 28202063, 2017). "Other involved pathways were again cell cycle signaling (15%, CDK6, CDK12), Fanconi anemia/DNA repair (15%, FANCD2, NBN), and additionally peroxisome proliferator-activated receptor (PPAR) signaling (8%, PPARG) as well as discoid in domain receptor 2 signaling (8%, DDR2)." (PMID 34200508, 2021).
pancreatic cancer (10 papers, 2017 to 2024). "There is also a suggestive case report showing a potential involvement of GPVs of PALB2 and NBS1 (NBN) in the susceptibility to pancreatic cancer." (PMID 35008774, 2021). "Here, we present the case of a female patient harboring pathogenic variants of PALB2 and NBN, with a family history of multiple pancreatic cancer in her younger brother, her aunt, and her father." (PMID 33413558, 2021). "Next, patient 84 harbored the variant (c.511A > G, p.Ile171Val, and rs61754966) in the NBN gene, which is a low penetrance risk factor for cancer development; the patient reported having a family history of breast and pancreatic cancer." (PMID 32695137, 2020). "The variant of C. 657DEL5 in the NBN gene increases the risk of pancreatic cancer." (PMID 35433762, 2022). "Finally, the patient’s daughter underwent genetic counseling and was found to harbor only the NBN c.265C > T(p.Arg89*) pathogenic variant, which was probably associated with breast, ovarian, pancreatic cancer." (PMID 33413558, 2021). "Furthermore, we informed them that their mother harbored the NBN pathogenic variant, which was potentially associated with breast, ovarian, and pancreatic cancer." (PMID 33413558, 2021). "In addition, the c.657del5 variant in the NBN gene was reported as associated with pancreatic cancer predisposition." (PMID 28402931, 2017). "PACCs have been shown to harbor DDR/HR DNA repair defects, but somatic loss of NBN has not been linked to the development of pancreatic cancers in general, or specifically to PACC." (PMID 38561473, 2024). "Except for MSH3, the rest of the germline mutant genes in non-BRCA carriers with TNBC were involved in the HRR pathway, including BLM, PALB2, NBN, RAD51C, and RAD51D, with the mutation rate of 9.26% (5/54), which increased the risk of other cancers, such as PLAB2 for pancreatic cancer." (PMID 33194720, 2020). "MGPTs generally cover at least 10 common HR-related genes such as ATM, BARD1, BRCA1, BRCA2, BRIP1, CHEK2, NBS1 (NBN), PALB2, RAD51C, and RAD51D, all of whose germline alterations are associated with BRCAness phenotypes for predisposition to breast, ovarian, prostate, or pancreatic cancer." (PMID 35008774, 2021).
melanoma (9 papers, 2013 to 2025). A malignant, usually aggressive tumor composed of atypical, neoplastic melanocytes. "Following our prior identification of double-stranded break repair deficiency in a subset of triple-wild-type cutaneous melanoma, we identified MRE11 and NBN loss-of-function SVs in melanomas with this mutational signature." (PMID 38758740, 2024). "The highest prevalence of germline mutations in our melanoma patients was found in the NBN gene (in 7/264 patients; 2.7%), coding for nibrin, a protein contributing to a MRN complex formation, sensing for DNA double strand breaks." (PMID 33050356, 2020). "Two of our melanoma patients (diagnosed with melanoma at 9 and 47 years, respectively; both with a melanoma-positive family cancer history) carried other rare NBN truncations." (PMID 33050356, 2020). "Altogether, 7/11 double mutation carriers (excluded from the analysis of clinicopathological data) carried at least one mutation in high-risk melanoma (POT1/CHEK2) or syndromic (ATM/WRN, BRCA1, BRCA2 (2x), CHEK2/RAD51D, NBN) genes." (PMID 33050356, 2020). "A total of 9 patients (3.4%) carried mutations in high-to-moderate melanoma risk genes (CDKN2A, POT1, ACD) and 22 (8.3%) patients in other cancer syndrome genes (NBN, BRCA1/2, CHEK2, ATM, WRN, RB1)." (PMID 33050356, 2020). "According to the TGCA database, all these genes are involved in melanoma; where NBN is particularly altered in uveal melanoma." (PMID 27057633, 2016). "Arm-level gene alterations in chromosome 8q21-24, where RAD21, NBN, and MYC are located, were found in approximately one fourth of mucosal melanomas." (PMID 39823560, 2025). "The cBioPortal database showed that MYC, NBN and KDR predicted poor survival of melanoma patients." (PMID 35688842, 2022). "To determine whether melanomas that have dysregulation of the MRN complex or ATM may be sensitive to PARP inhibitors, we performed independent knockouts of ATM, NBN, and MRE11 in 2 melanoma cell lines, MeWo (TWT) and A375 (BRAF-mutant), followed by olaparib cell viability assays." (PMID 38758740, 2024). "Currently, the variation and role of NBN in melanoma has not been reported." (PMID 35688842, 2022).
microcephaly (8 papers, 2014 to 2021). A congenital or acquired developmental disorder in which the circumference of the head is smaller than normal for the person's age and sex. "For example, a mouse model of the Nijmegen breakage syndrome gene NBN exhibited increased neuronal apoptosis, leading to microcephaly and decreased body mass." (PMID 32053595, 2020). "In this study we present NBS fibroblasts and iPSCs as a screening platform for anti-oxidants and a model for studying NBN de-regulation in cancer and microcephaly." (PMID 28790359, 2017). "Our study demonstrates the utility of NBS-iPSCs as a screening platform for anti-oxidants capable of suppressing DNA damage and a cellular model for studying NBN de-regulation in cancer and microcephaly." (PMID 28790359, 2017).
hereditary cancer (7 papers, 2014 to 2023). Malignant neoplasms occurring in families at a rate greater than that expected by chance and caused by germline mutations in a specific gene. "Analysis of hereditary cancer cases (732 BC patients, 189 CRC patients, and 490 cancer-free elderly controls) revealed that 1% presented concurrent germline pathogenic variants in BRCA1, BRCA2, MUTYH, ATM, CHECK2, NBN, and RAD50." (PMID 37628631, 2023).
Immunodeficiency (7 papers, 2015 to 2021). Failure of the immune system to protect the body adequately from infection, due to the absence or insufficiency of some component process or substance. "Mutations in the NBN gene (also called NBS1) are responsible for the Nijmegen breakage syndrome (NBS), which is characterized by spontaneous chromosomal instability, immunodeficiency, and a predisposition to cancer." (PMID 32824581, 2020). "Although it is not impossible for a patient to have two primary immune disorders, NBN mutations fully explain the low T cells, absent nibrin and cellular radiosensitivity that establish the diagnosis of NBS in this patient, while the features of CD40L deficient hyper-IgM syndrome are absent." (PMID 25677497, 2015).
Lynch syndrome (7 papers, 2017 to 2026). An autosomal dominant hereditary neoplastic syndrome characterized by the development of colorectal carcinoma and a high risk of developing endometrial carcinoma, gastric carcinoma, ovarian carcinoma, renal pelvis carcinoma, and small intestinal carcinoma. "Of these, five mutations (9.26%, 5/54) were in homologous recombination repair (HRR) pathway genes, including PALB2 (1.85%, 1/54), BLM (1.85%, 1/54), NBN (1.85%, 1/54), RAD51C (1.85%, 1/54), and RAD51D (1.85%, 1/54), and one mutation was in MSH3 (1.85%, 1/54) related to Lynch syndrome." (PMID 33194720, 2020).